RBP4 (retinol binding protein 4)
Diseases named in the same sentence as RBP4 in open-access papers (continued):
Sharing a sentence is not in itself a finding about the gene and the disease.
Obesity (continued). "Similarly, circulating RBP4 levels predicted the development of metabolic syndrome and its components, including IR, in adolescents, irrespective of obesity." (PMID 32718041, 2020). "Strong, positive correlations between RBP4 levels and triglycerides, which constitute two major lipid abnormalities in both T2D and metabolic syndrome individuals, were observed in patients with and without obesity." (PMID 32718041, 2020). "Therefore, increased RBP4 levels in the blood of patients with obesity and metabolic diseases does not mean increased levels of retinol." (PMID 33198782, 2020). "Other authors demonstrated that HFD can induce LGR5 expression, stem cell transformation, and colon carcinogenesis in a xenograft model of colon cancer independent of obesity through a vitamin A-bound serum retinol binding protein 4-stimulated by retinoic acid 6 (RBP4-STRA6) signalling pathway." (PMID 31816977, 2019). "RBP4 is more markedly expressed in visceral fat rather than subcutaneous fat, and RBP4 expression in visceral fat is significantly increased in individuals with obesity and T2DM." (PMID 31208019, 2019). "In all subjects combined, as well as in T2DM subjects and non-diabetic subjects separately, RBP4 and retinol were unrelated to age, blood pressure, obesity measures and glycemic control, except for a positive correlation of RBP4 with age in non-diabetic subjects." (PMID 31717719, 2019). "We noted that RBP4 levels in boys increased consistently across puberty regardless of their weight status; whereas in girls, this increase in RBP4 across puberty was only evident in the absence of obesity, suggesting a sexual dimorphism in RBP4 levels with regard to obesity." (PMID 29759068, 2018). "When subjects were divided into four groups according to BMI and estrogen (E2) stratified by the median values, the highest value for serum RBP4 was in subjects with both obesity and the low estrogen level, the lowest value was in non-obese groups with high estrogen level." (PMID 26960804, 2016). "However, data in humans have been controversial; serum RBP4 levels are reportedly elevated with IR in patients with obesity and CVD, but other authors have failed to confirm these findings." (PMID 24932224, 2014). "The most striking, novel finding of the present study is that RBP4 levels measured in childhood were strong predictors of the subsequent development of MS and each of its components (including IR, hyperglycemia, hypertension and hyperlipidemia) 10 years later, independent of obesity." (PMID 29759068, 2018). "This cross-sectional study has the novelty of showing the relationship between the characteristics of the obesogenic environment and non-traditional biomarkers of obesity in children, such as body adiposity assessed by DXA and pro-inflammatory adipokines (leptin and RBP4)." (PMID 37559196, 2023). "Overall, significant negative correlations were observed for UCN1 expression and obesity markers (BMI, percentile, body fat percentage, and cholesterol), for UCN3 and TNFα and NGAL, as well as for CRH and TNFα, RBP4, ZAG, and circulating UCN2 levels (p < 0.05)." (PMID 35276788, 2022). "However, a previous study has shown that circulating RBP4 and TTR were not affected by human obesity or T2DM, compared to lean controls." (PMID 25142320, 2014). "However, FEN has also been shown to reduce obesity and hyperleptinaemia in mice lacking RBP4, implying that the anti-obesity effects of FEN are most likely to be independent of its ability to decrease circulating RBP4 levels." (PMID 26592777, 2016).
diabetes (147 papers, 2009 to 2026). "In individuals with diabetes, RBP-4 has demonstrated an association with the development of atherosclerotic risk factors, including inflammation." (PMID 40278353, 2025). "RBP4 was linked to NAFLD in patients with type 2 diabetes mellitus (T2DM) (OR 1.155, 95% CI 1.012-1.318)." (PMID 40525016, 2025). "Concretely, elevated levels of RBP4 in urine have been associated with various renal pathologies, including glomerulopathies, diabetes, renal allograft dysfunction, chronic kidney disease, and preeclampsia." (PMID 39795999, 2024). "They found that parental diabetes was associated with lower adiponectin but higher RBP4 concentrations in offspring." (PMID 38520616, 2024). "After adjusting for age, sex, education, activity, alcohol use, smoking, hypertension history, and diabetes history (Model 1), participants in the 4th quartile of RBP4 had a 3.467-fold increased risk of CKD compared to those in the 1st quartile (P<0.001)." (PMID 39698033, 2024). "The present meta-analysis aimed to determine the diagnostic potential of RBP4 in patients in type 2 diabetes mellitus (T2DM) with DN." (PMID 38711978, 2024). "Diabetes problems such as retinopathy, cardiovascular problems, nephropathy, and non-alcoholic fatty liver have been associated with RBP4 in several research." (PMID 37123774, 2023). "RCSdisplayed a positive linear correlation between RBP4 levels and the risk of DCMin diabetes (p = 0.004)." (PMID 39076230, 2022). "Several prospective cohort studies reported that serum RBP4 levels were associated with increased risk of diabetes and cardiovascular mortality in men with type 2 diabetes." (PMID 35634496, 2022). "Chiglitazar showed a greater improvement in parameters of diabetes than sitagliptin, and changes in serum RBP-4 levels were associated with changes in insulin-sensitizing parameters." (PMID 35547000, 2022). "Several studies have suggested a potential association between elevated RBP4 levels and the development of diabetes complicated with cardiovascular diseases." (PMID 35082965, 2022). "In the current study, we found plasma glucose concentrations in non-diabetes were associated with RBP4 levels as expected." (PMID 35634496, 2022). "When controlled with eGFR,diabetic nephropathy and other parameters, we still found RBP4 is the risk factorfor DCM in patients with diabetes." (PMID 39076230, 2022). "The associations between circulating RBP4 levels, diabetes mellitus and other chronic diseases have been well documented." (PMID 34419052, 2021). "In T2DM patients, RBP4 levels were positively correlated with sICAM-1 and sE-selectin, which were related to the progression of vascular complications associated with diabetes." (PMID 32718041, 2020). "Age-, sex- and diabetes status-adjusted multivariable linear regression analysis revealed that RBP4 was independently associated with large VLDL (β = 0.444, p = 0.005) and small LDL particles (β = 0.539, p < 0.001)." (PMID 31717719, 2019). "After exclusion of patients with diabetes, patients with elevated RBP4 concentrations were correlated with higher risk of CAD even after adjustment for the confounders (adjusted OR = 1.82, 95%CI = 1.46 – 2.13, P < 0.001)." (PMID 31278889, 2019). "Further adjusting for menopausal status in women made little impact on the RBP4-diabetes association in women (OR per log RBP4 was 2.84; 95% CI 1.09–7.42)." (PMID 30651745, 2019). "In recent years, most research efforts have been focused on studying diabetes associated insulin-sensitizing adipokines, such as adiponectin (also known as Acrp30), vaspin visfatin, metrnl (also known as subfatin), and retinol binding protein 4 (RBP4)." (PMID 28659972, 2017). "Univariate analysis showed that TNM stages (P<0.001), tumor metastasis (P<0.001), diabetes (p=0.049), BMI (P=0.030), iFOBT (p=0.012) and RBP4 (p=0.022) associated with overall survival rates." (PMID 29190912, 2017).
diabetes (continued). "And a cross-sectional study conducted in Chinese found that increased RBP4 levels increased the risk for hyperglycemia, including impaired glucose regulation and newly diagnosed type 2 diabetes mellitus, even after adjustment for a number of confounders." (PMID 24160775, 2013). "When patients were stratified by diabetes status, univariate Cox regression analysis revealed a consistent inverse association between RBP4 levels and all-cause mortality across both baseline and longitudinal quartiles in both type 2 diabetes mellitus (T2DM) and non-T2DM groups." (PMID 40881125, 2025). "In addition, other meta-analyses demonstrated that serum RBP4 concentrations in patients with T2DM are associated with diabetes-related renal dysfunction and diabetic retinopathy." (PMID 38520616, 2024). "As a result, RBP-4 can be used to predict diabetes risk as well as cardiovascular events." (PMID 37892122, 2023). "Similarly, in our present study, we found that RBP4 was significantly associated with a long-term waist circumference level in non-diabetes, a commonly used proxy for visceral fat." (PMID 35634496, 2022). "After adjustment for traditional risk factors, RBP4 level was a clear predictor of future diabetes." (PMID 31690939, 2020). "Furthermore, inherent to the limitation of the methodology, the temporal relation between RBP4 and the risk of diabetes cannot be established from cross-sectional studies." (PMID 30651745, 2019). "Furthermore, we have observed a stronger RBP4-diabetes association among women with low levels of ALT or ferritin levels (< median values) in the current study." (PMID 30651745, 2019). "In contrast, another 6-year follow-up study among 2091 Chinese men and women, with 507 cases of type 2 diabetes, has shown a positive RBP4-diabetes association in the overall population, and the HR comparing the highest versus lowest quintile of RBP4 concentration was 1.47 (95% CI 1.07–2.03)." (PMID 30651745, 2019). "Third, since the majority of patients with classical cardiovascular risk factors (e.g. diabetes, dyslipidemia, hypertension etc.)were already treated, we cannot rule out the plausible effects of pharmaceutical agents (e.g. statins) on RBP4, leading to underestimation of its predictive power." (PMID 30038059, 2018). "Since the majority of patients with classical cardiovascular risk factors (e.g. diabetes, dyslipidemia, hypertension etc.)were already treated, we cannot rule out the plausible effects of pharmaceutical agents (e.g. statins) on RBP4, leading to underestimation of its predictive power." (PMID 25142320, 2014). "Previous studies reported that SNPs of RBP4 could increase diabetes susceptibility and decrease insulin secretion and insulin sensitivity." (PMID 24665145, 2014). "The increased serum RBP4 concentrations in type 2 diabetic patients may be associated with diabetes-related renal dysfunction, cardiovascular disease and imbalances in lipid metabolism." (PMID 26237391, 2014). "In addition, a functional polymorphism in the RBP4 gene associated with increased serum RBP4 was found in a Mongolian population suffering rapid increase of diabetes." (PMID 22567167, 2012). "We also analyzed whether the promoter SNPs in RBP4 (rs3758538 and rs3758539) are associated with diabetes related phenotype in our population." (PMID 20625434, 2010). "Other genetic studies with SNPs in RBP4 have reported association with serum lipid parameters but in our study we failed to observe any significant association of the promoter polymorphisms with serum lipid levels or with other diabetes related parameters." (PMID 20625434, 2010). "In addition, recent studies have shown that RBP4 may be involved in insulin resistance and diabetes, conditions that are often associated with diabetic nephropathy." (PMID 39795999, 2024).
diabetes (continued). "Liraglutide, one of the glucagon-like peptide-1 (GLP-1) analogs that could decrease post-prandial glucose level by regulating incretin in type 2 diabetes, reduced RBP4 gene expression in adipose tissue in mice, which might contribute to the reduction of cardiovascular risk in diabetes." (PMID 35634496, 2022). "Moreover, genetic studies have identified an RBP4 promoter polymorphism that increases RBP4 expression and is associated with a ~2-fold increased risk for type 2 diabetes, suggesting that elevated RBP4 levels contribute to diabetes in certain human populations." (PMID 25918733, 2015). "RBP4 is tightly related to several rheumatic disease comorbidities, like diabetes and cardiovascular pathologies." (PMID 38275649, 2024). "The clinical phenotype enrichment showed that the proteomic profile of the RBP4-treated hOACs exhibited significant similarities with arthritis and diabetes mellitus clinical proteomic profiles." (PMID 38275649, 2024). "For this purpose, the expression of RBP4 has been studied in five experimental groups of mice: controls, diabetics, insulin-treated diabetics, mice that overexpress PTHrP at the renal level, and a group of diabetics." (PMID 39795999, 2024). "Our results show that RBP4 and PTHrP levels are elevated in both diabetes and lipotoxic PA damage in podocytes." (PMID 39795999, 2024). "Specifically, as patients with prediabetes have a greater risk of developing diabetes, with a lifetime conversion rate to T2DM as high as 74%, several studies have focused on the early diabetes-predicting role of RBP4 in individuals with prediabetes." (PMID 38520616, 2024). "Retinol binding protein 4 (RBP4) is an adipokine that has been explored as a key biomarker of type 2 diabetes mellitus (T2DM) in recent years." (PMID 38520616, 2024). "One study tested RBP4 levels in diabetes patients with microalbuminuria and found that RBP4 concentrations were significantly elevated in the plasma of diabetes patients, with notably higher levels observed in those with microalbuminuria." (PMID 39698033, 2024). "The RBP4 levels of shift workers increased by an average of 9.51 μg/mL compared with the day shift, when age, gender, BMI, diabetes, PSQI, family income, smoking and drinking remained unchanged in the last multivariate linear mixed models." (PMID 37312059, 2023). "In logistic regression models, RBP-4, Col1,and HGF were associated with increased albuminuria(UACR ≥ 3.0 mg/mmol) after adjustment for age, sex, BMI, duration of diabetes, and HbA1C." (PMID 36836700, 2023). "RBP4 plays a key role in glucose homeostasis and GLUT transporter efficiency, linking altered metabolic states to diabetes risk." (PMID 36833129, 2023). "More comprehensive studies, particularly cohort studies, are needed to explore other potential risk factors linking shift work with RBP4 and T2DM, aiding in mitigating diabetes risk among shift workers." (PMID 37312059, 2023). "There is significant difference of AUROC between RBP4 and NT-proBNP for diagnoseDCM of diabetes (p < 0.001)." (PMID 39076230, 2022). "For example, an AuPt/ZIF-67 NPs-based ECL system was developed in order to detect the retinol-binding protein 4 (RBP4), a type 2 diabetes mellitus-specific biomarker." (PMID 36140123, 2022). "Recently, fetuin A, fatty acid binding protein 4 (FABP4) and retinol binding protein 4 (RBP4) were identified as biomarkers of atherosclerotic cardiovascular disease and diabetes." (PMID 36561568, 2022). "Reclassification and discrimination statistics for diabeticcardiomyopathy by serum RBP4 in patients with diabetes mellitus." (PMID 39076230, 2022). "Risk of diabetic cardiomyopathy according to tertiles ofserum retinol binding protein 4 and NT-proBNP levels in patients with diabetes." (PMID 39076230, 2022).
diabetes (continued). "Adding log RBP4 to a basic riskmodel including age, BMI, diabetes duration, LVEF, insulin treatment, TG, LDL-C,eGFR, CRP, log NT-proBNP, retinopathy, nephropathy and neuropathy improved thec-index from 0.91 to 0.94 (p = 0.024)." (PMID 39076230, 2022). "The presence of symptomatic PAD was significantly correlated with age, diabetes, hsCRP, RBP4 and low adiponectin levels (p < 0.05)." (PMID 34758835, 2021). "Retinol binding protein 4 (RBP4) has been regarded as an important serological biomarker for type 2 diabetes mellitus (T2DM)." (PMID 34496877, 2021). "It has been reported that the serum level of RBP4 in individuals with diabetes is significantly higher than that in healthy individuals; moreover, it increases with a decline in renal function." (PMID 34669736, 2021). "The levels of plasma RBP4 in patients with impaired glucose tolerance and type 2 diabetes mellitus were significantly higher than that in the control (CON) groups." (PMID 34177800, 2021). "In the whole study cohort, the presence of symptomatic PAD was significantly correlated with age, diabetes, hsCRP, RBP4 and low adiponectin levels (p < 0.05)." (PMID 34758835, 2021). "Retinol-binding protein 4 activator decrease the concentration of RBP4 and thereby improves insulin sensitivity in diabetes." (PMID 32864980, 2020). "When we analyzed the correlation between BCAA and RBP4 variation with diabetes markers depending on the group the subjects were allocated to, the glucose variation showed a significant relationship with BCAA variation only in the intervention group." (PMID 32178221, 2020). "For example, the expression levels of genes relevant to cholesterol and lipoprotein transport, such as Apoa1-2/Apoc1-3/Lcn2/Rbp4, showed reversed phase between the diabetes and diabetes-DFE groups." (PMID 31790971, 2020). "The purpose of this study was to perform a systematic review and meta-analysis of the role of circulating retinol-binding protein 4 (RBP4) in the type 2 diabetes mellitus (T2DM) patients with kidney diseases." (PMID 33082885, 2020). "In the present study, an ultrasensitive aptasensor for monitoring RBP4 at the detection limit of 951 fg/mL was designed and applied for predicting diabetes at early stages." (PMID 31953481, 2020). "Another study compared the SG to roux-en-y gastric bypass(GBP) in subjects with diabetes, the results showed that RBP4 was significantly decreased as early as 3 days after GBP." (PMID 31956345, 2020). "It should be emphasized that increased levels of RBP4 in patients with diabetes are considered as a marker of renal tubular dysfunction." (PMID 32156052, 2020). "In age-, sex- and diabetes status-adjusted analysis, RBP4 and retinol were independently related to large VLDL and small LDL (models A and B)." (PMID 31717719, 2019). "Available data focusing on the relationship of RBP4 and type 2 diabetes mellitus, PCOS, and ovarian cancer have been originated from population-based prospective studies." (PMID 31412686, 2019). "Since Cbl signalling is compromised in diabetes, these data highlight a novel mechanism that upregulates RBP4 locally." (PMID 29114012, 2018). "Retinol-binding protein 4 (RBP4) expression was enhanced in patients with diabetes and its increase was correlated with retinal neuronal degeneration, early-onset of microglia activation and increased expression of pro-IL-18 and activated IL-18." (PMID 29301251, 2018). "In multivariate logistic regression analysis, we calculated the prognostic value of RBP4 levels in diabetic stroke patients and diabetes-free stroke patients." (PMID 30038059, 2018). "The data suggested that plasma levels of RBP4 in patients with diabetes were significantly higher than in normal controls (28.6 (IQR: 18.1–38.0) μg/ml compared with 15.5 (IQR: 11.0–22.8) μg/ml; P<0.001)." (PMID 30135138, 2018).